SIRT1 (sirtuin 1)
Diseases named in the same sentence as SIRT1 in open-access papers (continued):
Sharing a sentence is not in itself a finding about the gene and the disease.
ischemia (continued). "In the present study we assessed the role of miR-200c on CA1 neurodegeneration, sirtuin-1 (SIRT1), and mitochondrial dynamic protein expression in a mouse model of transient global cerebral ischemia and in vitro in primary mouse astrocyte cultures after simulated ischemia." (PMID 36466801, 2022). "Furthermore, it is not yet clear how an increase in the expression of NAD+-dependent SIRT1 or stimulation of its activity for neuroprotection will affect the early stages of ischemia, when mitochondrial function is disrupted and a strong energy deficit is observed." (PMID 35574497, 2022). "These oscillatory patterns were however disturbed in macrophages and neutrophils post-MI, which may be explained by alterations to the circadian clock network, in particular Sirt1 expression, which is shown to be downregulated in murine models of ischemia/reperfusion after a MI." (PMID 35694249, 2022). "Therefore, in the present study, we aimed to test if XFZY might contribute to the protection of ischemic myocardial cells induced by ischemia through SIRT1-mediated signal transduction pathway by using electron micrograph, RT-PCR assay, and western-blot test." (PMID 25114706, 2014). "The present study investigated the altered distribution of short‐form SIRT1 and SIRT3 in young and aged hearts during acute ischemia and long‐term I/R stress." (PMID 37537789, 2023). "We further examined the effects of cardiomyocyte SIRT1 and SIRT3 deletion on the mitochondrial structure of the AAR in hearts' left ventricles under sham operation, acute ischemia, and I/R stress." (PMID 37537789, 2023). "In aged hearts, SIRT1 translocated into mitochondria and recruited more mitochondria SIRT3 to enhance their interaction during acute ischemia, acting as adaptive protection for the aging hearts from further mitochondria dysfunction." (PMID 37537789, 2023). "Hypermethylation of sirtuin 1 (Sirt1) via DNMT3A contributed to a lower expression of Sirt1 and ischemia-sensitive heart in GDM offspring in later life." (PMID 37255932, 2023). "Our results showed that Sal B, a promising drug for PAD, improved limb ischemia via M2 macrophage polarization by the SIRT1/PI3K/AKT pathway, thereby exerting an antilimb ischemia effect." (PMID 35656466, 2022). "To determine the cellular distribution of SIRT1, p-JNK, and caspase-3 in rats following ischemia, we immunostained paraffin-embedded brain sections of sham controls and MCAO (24 h) rats from both the age groups (young and aged rats)." (PMID 33737560, 2021). "Myocardial ischemia significantly increased acetylation of FoxO1, a major target of Sirt1, whereas NMN significantly attenuated ischemia-induced increases in FoxO1 acetylation." (PMID 24905194, 2014). "Nicotinamide phosphoribosyltransferase (Nampt), the rate-limiting enzyme for nicotinamide adenine dinucleotide (NAD+) synthesis, and Sirt1, an NAD+-dependent histone deacetylase, protect the heart against ischemia/reperfusion (I/R)." (PMID 24905194, 2014). "SIRT1 is also activated in the heart following IPC and provides cardioprotection from ischemia and coronary artery occlusion." (PMID 23730259, 2012). "In myocardial ischaemia-reperfusion injury, miR-30a-5p exacerbates myocardial damage through the circ_0002612/miR-30a-5p/Ppargc1a/NLRP3 axis, while its inhibition can enhance mitochondrial function by activating SIRT1." (PMID 40504789, 2025).
ischemia (continued). "Moreover, resveratrol is thought to indirectly enhance SIRT1 activity through cAMP and AMPK signaling, modulating the cAMP/AMPK/SIRT1 pathway to reduce energy expenditure during ischemia and provide neuroprotection." (PMID 40356977, 2025). "In addition, SIRT1-induced Nrf2 activation upregulated NOX4, HIF-1α, and VEGF expression following intestinal ischemia/reperfusion, leading to increased angiogenesis, cell viability, and migration of human PMECs." (PMID 39598406, 2024). "Thus, SIRT1 plays a role in modulating SIRT3‐mediated mitochondrial function and substrate metabolism to adapt to myocardial acute ischemia and I/R stress." (PMID 37537789, 2023). "In the left hippocampus and in both right and left cortex, both pre- and post-ischemia melatonin treatments did not increase SIRT1 levels." (PMID 30029514, 2018). "Interestingly, SIRT1 was directly correlated with basal HBF (P = 0.0265), HBF post-heating (P = 0.0052), HBF post-ischemia (P = 0.0019), basal FBF (P = 0.0148), FBF post-heating (P = 0.0030), and FBF post-ischemia (P = 0.003)." (PMID 37848614, 2023). "Interestingly, mitochondrial SIRT1 decreased in aged AAR under sham conditions versus the young group, while there were more SIRT1 translocated into mitochondria in aged hearts upon acute ischemia." (PMID 37537789, 2023). "Thus, the growth of SIRT1 and SIRT2 levels in neurons and of SIRT1 in astrocytes of penumbra, as well as the redistribution of SIRT1 to neuronal cytoplasm, undoubtedly indicate the involvement of these sirtuins in the response of brain cells to ischemia." (PMID 35574497, 2022). "Continued experiments showed that exosomal circSHOC2 could be transmitted to neurons and inhibit neuronal apoptosis by promoting autophagy via sponging miR-7670-3p and subsequently increasing sirtuin 1 (SIRT1) levels, contributing to the healing of ischemia-induced brain injury." (PMID 36009062, 2022). "The studies presented indicate the involvement of these sirtuins in the response of brain cells to ischemia in the first 24 h, but the alterations in their expression and change in the localization of SIRT1 are not related to the regulation of penumbra cell apoptosis in the acute period after PTS." (PMID 35574497, 2022). "Except for SIRT1, AMPK has also been demonstrated to promote NO secretion by increasing eNOS phosphorylation as serine 633, which was another effective way for SIRT1 to overcome caloric restriction and facilitate vascular reconditioning after ischemia via activating the AMPK/eNOS axis." (PMID 33304318, 2020). "Whether cardioprotection induced by exogenous AD administration may involve SIRT-1 activity is not known; however, the protective role of SIRT-1 during ischemia and the potential interplay between AMPK and SIRT-1 suggest this possibility." (PMID 30653603, 2019).
pancreatic cancer (83 papers, 2011 to 2025). "Research in pancreatic cancer has demonstrated that a loss of SIRT1 correlates with reduced expression of glycolytic pathway proteins like GLUT1 and decreased cancer cell proliferation." (PMID 38178094, 2024). "Future studies should be conducted to understand ERRα and SIRT1 interaction at a genomic and protein level, to identify the underlying mechanism by which its expression is regulated in pancreatic cancer." (PMID 34907162, 2021). "SIRT1 upregulation has been observed in pancreatic cancers and is associated with worse overall survival rates in patients with pancreatic cancer." (PMID 34163012, 2021). "At both mRNA and protein levels, SIRT1 overexpression in pancreatic cancer tissue is apparently associated with tumor size, stage, and presence of lymph node or liver metastases." (PMID 27379175, 2016). "Our findings indicate that targeted inhibition of SIRT1 or HSF1 could serve as a promising strategy to sensitize BAP1-deficient pancreatic cancer subtypes to immunotherapy." (PMID 39350280, 2024). "For example, the activation of SIRT1 hasbeen found to increase proliferation, invasion, and accelerateepithelial-mesenchymal transition in pancreatic tumor cells,which is associated at least in part with suppression of geneexpression of the FOXO3 and GRHL3 transcription factors." (PMID 38680178, 2024). "In the current study, we found that downregulation of miR-138-5p was associated with induced autophagy in human pancreatic cancer tissues; however, restored expression of miR-138-5p inhibited the SIRT1/FoxO1/Rab7 pathway-dependent autophagy and subsequent apoptotic cell death." (PMID 28052003, 2017). "This study sought to establish whether SIRT1-7 protein expression was associated with clinico-pathological features in pancreatic cancer, and to determine their potential use as prognostic/predictive markers." (PMID 26121130, 2015). "Additionally, it suggests that SIRT1 inhibition combined with ICB therapy may ameliorate the unresponsiveness of BAP1-deficient pancreatic cancer to single-agent immunotherapy." (PMID 39350280, 2024). "Mechanistically, HIF-1α-induced exosomal circZNF91 is transferred to normoxic pancreatic cancer cells and serves as a ceRNA of miR-23b-3p, thereby relieving the inhibitory effects of miR-23b-3p on Sirtuin1 (SIRT1) expression." (PMID 40004471, 2025). "Targeting SIRT1 to modulate these pathways holds significant therapeutic promise in overcoming the resistance mechanisms inherent to pancreatic cancer." (PMID 39682281, 2024). "SIRT1, as a key modulator of apoptotic pathways and cell survival, plays a pivotal role in pancreatic cancer’s resistance to chemotherapy." (PMID 39682281, 2024). "Leng S., Huang W., Chen Y., Yang Ya., Feng D., Liu W., Gao T., Ren Y.,Huo M., Zhang J., Yang Yu., Wang Y. SIRT1 coordinates with theCRL4B complex to regulate pancreatic cancer stem cells to promotetumorigenesis." (PMID 38680178, 2024). "In summary, SIRT1 emerges as a pivotal regulator in pancreatic cancer through its multifaceted roles in tumor progression and resistance mechanisms." (PMID 39682281, 2024). "This signaling cascade, coupled with adiponectin’s elevation of β-catenin, underscores SIRT1’s critical role in linking metabolic and oncogenic pathways, positioning it as a key regulator in the survival and proliferation of pancreatic cancer cells." (PMID 39682281, 2024). "The downregulation of β-catenin via SIRT1 activation effectively inhibits pancreatic cancer cell proliferation, highlighting the therapeutic potential of SIRT1 in targeting β-catenin-driven oncogenic pathways in pancreatic cancer." (PMID 39682281, 2024). "In conclusion, targeting the sirtuin family, SIRT1—7, represents a comprehensive strategy for tackling pancreatic cancer’s complex biology." (PMID 39682281, 2024).
pancreatic cancer (continued). "miR-373 can specifically target the 3′-UTR of SIRT1, reduce its expression in pancreatic cancer cells, and exert anti-proliferation and pro-apoptosis effects on pancreatic cancer cells." (PMID 36950520, 2023). "miR-373 is a tumor suppressor miRNA that inhibits proliferation of pancreatic cancer cells through influencing activity of SIRT1/PGC-1α/NRF2 axis." (PMID 37441551, 2023). "In pancreatic cancer, hypoxic exosomal circZNF91/miR-23b-3p/SIRT1/HIF-1a formed a positive feedback loop that co-regulates gemcitabine resistance in pancreatic cancer cells under hypoxia." (PMID 37213665, 2023). "For example, miR-138-5p was ascertained to suppress autophagy in pancreatic cancer through targeting SIRT1." (PMID 35101035, 2022). "The knockdown or pharmacological inhibition of Nox4 activity abolishes tumor-induced cachexia in mice, suggesting that targeting the SIRT1-Nox4 axis in muscles mitigates cachexia in pancreatic cancer." (PMID 36077789, 2022). "In cachectic muscles, tumor-induced SIRT1 loss leads to the activation of NF-κB, which upregulates NOX4 expression to exaggerate pancreatic tumor-induced cachexia." (PMID 35646942, 2022). "Along with the orphan nuclear receptor ERRα, Tnni2 was identified as a crucial protein contributing to increased cell proliferation, migration and invasion of pancreatic cancer by up-regulation of Sirt1 and downstream Syt8." (PMID 36077344, 2022). "For example, SIRT1 can promote the pancreatic cancer progression by regulating cell proliferation, chemosensitivity, and acinar-to-ductal metaplasia." (PMID 35422493, 2022). "Restored expression of miR-138-5p suppresses autophagy in pancreatic cancer by targeting SIRT1 and thus suppresses pancreatic cancer cell proliferation." (PMID 36572911, 2022). "In this study, we further confirmed that SIRT1 can promote mesenchymal marker expression, downregulate epithelial marker expression, and promote pancreatic cancer cell invasion, thus emphasizing its positive role in the induction of EMT." (PMID 34163012, 2021). "The results also implicate the SIRT1/CRL4B complex in pancreatic cancer metastasis and stem cell properties, thus supporting SIRT1 as a promising potential target for cancer therapy development." (PMID 34163012, 2021). "Here, we reported that SIRT1 is physically associated with CRL4B complex and promotes pancreatic cancer cell proliferation, invasion, and autophagy." (PMID 34163012, 2021). "In summary, these results showed a direct correlation between TNNI2 and the ERRα/SIRT1 signaling pathway and its role in altering cell characteristics in pancreatic cancer cell lines." (PMID 34907162, 2021). "Elevated SIRT1 expression has been associated with poorly differentiated pancreatic ductal carcinomas and poor disease outcomes and SIRT1 has been shown to promote pancreatic cancer cell proliferation, invasion and autophagy." (PMID 34907162, 2021). "Our findings indicated that the SIRT1/CRL4B complex functions as a whole, while co-phenotypic experiments with SIRT1 showed that CUL4B positively correlated with autophagy in pancreatic cancer." (PMID 34163012, 2021). "We collected 86 pancreatic carcinoma samples from pancreatic cancer patients and performed tissue microarrays via immunohistochemical staining, to examine the expression of SIRT1, CUL4B, and FOXO3." (PMID 34163012, 2021). "Despite the increasing evidence pointing to a critical role for SIRT1 in pancreatic cancer pathogenesis, the detailed mechanisms remain to be established, particularly in the development of pancreatic cancer stem cells (CSCs)." (PMID 34163012, 2021). "In contrast, chemical inhibition or knockdown of SIRT1 in pancreatic cancer cells reduces proliferation and induces apoptosis and senescence." (PMID 34907162, 2021).
pancreatic cancer (continued). "Our data indicated that SIRT1 is essential for pancreatic cancer tumorigenesis and maintenance of stemness, supporting the pursuit of SIRT1 as a target for cancer therapeutic strategies." (PMID 34163012, 2021). "In this study, we demonstrated that SIRT1 cooperates with the CRL4B complex in transcriptional inhibition, also participating in various biological processes associated with pancreatic cancer, including proliferation, autophagy, invasion, and stemness." (PMID 34163012, 2021). "In contrast, limited studies indicated that SIRT1 reduced cell proliferation and tumor formation in pancreatic cancer models." (PMID 34163012, 2021). "Although accumulating evidence indicates that sirtuin 1 (SIRT1) exerts biological functions in various cancers, how it contributes to tumorigenesis and metastasis of pancreatic cancer, as well as its role in CSCs, is still poorly defined." (PMID 34163012, 2021). "This demonstrates that SIRT1 dramatically induces stemness in pancreatic cancer cells, thus increasing the growth of established tumor xenografts." (PMID 34163012, 2021). "We transfected the SIRT1 overexpression construct into siSYT8-expressing BxPC-3 cells and siSIRT1 into SYT8-overexpressing PANC-1 cells to study the relationship between SYT8 and SIRT1 in pancreatic cancer." (PMID 34907162, 2021). "It has been reported that SIRT1 inhibits apoptosis and senescence and supports the viability, proliferation, and invasion of pancreatic cancer cells." (PMID 34163012, 2021). "In fact, serum starvation of pancreatic cancer in vitro induces increased SIRT1 activity and decreased levels and temporal patterns of expression of circadian clock genes in vitro." (PMID 33042011, 2020). "Its restitution using a systemic nanovector inhibits pancreatic cancer growth in mice and decreases SIRT1 expression." (PMID 33042011, 2020). "SIRT1 seems to be involved in the adaptive response of pancreatic cancer cells to chemotherapy-induced DNA damage stress." (PMID 33042011, 2020). "Given the importance of SIRT1 in pancreatic cancer regulation, it was expected that NAD synthesis and degradation had an important role in tumor cell metabolism and growth as well." (PMID 33042011, 2020). "SIRT1 is a very important regulator and potential therapeutic target in pancreatic carcinogenesis and in advanced pancreatic cancer." (PMID 33042011, 2020). "On the other hand, miR-138-5p suppresses autophagy by directly targeting SIRT1 expression and inhibits mTOR dephosphorylation under serum starvation-induced autophagy in pancreatic cancer." (PMID 33042011, 2020). "Ectopic expression of miR-217 inhibited TGF-β1-induced EMT by downregulating SIRT1 in chronic pancreatitis and pancreatic cancer, while miR-494 inhibited the proliferation, invasion and chemoresistance of pancreatic cancer by regulating SIRT1 and c-Myc." (PMID 33042011, 2020). "This SIRT1-selective inhibitor showed a strong antiproliferative effect in pancreatic cancer cells and enhanced sensitivity of cancer cells to gemcitabine treatment through increased apoptosis." (PMID 30761005, 2019). "SIRT1 was significantly upregulated in pancreatic cancer tissues and cell lines, and played a role in the regulation of pancreatic cancer cell proliferation and migration." (PMID 29752439, 2018). "SIRT1 plays a confirmed role in ovarian, thyroid, and pancreatic cancers, while its role in GC is yet to be definitely established." (PMID 30319549, 2018). "Further, we found that key nodes of regulation by our confirmed hits in this interaction map were known molecules that modulate survival, EMT and drug resistance in Ras mutated pancreatic cancers, such as YAP1, SIRT1, BAG3, ILK, CDK5, HDACs or GSK3β." (PMID 30325918, 2018). "For example, studies showed that inhibiting SIRT1 sensitized pancreatic cancer cells to gemcitabine through induction of DNA damage and apoptosis." (PMID 30451820, 2018).